PLS3 (plastin 3)
Description:
Actin-bundling protein.
Synonyms: T-plastin; BMND18; DIH5
Tractability: Small molecule: a structure with a bound ligand is known. Antibody: its Gene Ontology location is reachable by antibodies, with high confidence. PROTAC: ubiquitination databases record sites on it; its protein half-life has been measured.
Gene: Protein-coding gene on chromosome X (115,560,928 to 115,650,861, forward strand). Ensembl gene ENSG00000102024.
Subcellular location: Cytoplasm
Subcellular location (Human Protein Atlas): Cytosol; Plasma membrane
Gene Ontology:
Molecular function: actin filament binding; calcium ion binding; structural constituent of presynaptic actin cytoskeleton
Biological process: bone development; actin filament bundle assembly; presynaptic actin cytoskeleton organization; regulation of synaptic vesicle cycle
Cellular component: cytosol; actin filament; actin filament bundle; cytoplasm; neuromuscular junction
Homologues: Orthologues: chimpanzee PLS3 (100% identical), macaque PLS3 (99% identical), rabbit PLS3 (99% identical), dog PLS3 (99% identical), mouse Pls3 (99% identical), guinea pig PLS3 (99% identical), rat Pls3 (98% identical), pig PLS3 (90% identical), tropical clawed frog pls3 (88% identical), zebrafish pls3 (86% identical), Drosophila melanogaster Fim (54% identical), Caenorhabditis elegans plst-1 (31% identical), and 1 more. Paralogues in human: LCP1 (80% identical), PLS1 (75% identical).
Diseases named in the same sentence as PLS3 in open-access papers:
PLS3 is named in the same sentence as 69 diseases in open-access papers, as found by Europe PMC text mining. Sharing a sentence is not in itself a finding about the gene and the disease. The quoted sentences say what the papers report.
osteoporosis (41 papers, 2016 to 2026). A condition of reduced bone mass, with decreased cortical thickness and a decrease in the number and size of the trabeculae of cancellous bone (but normal chemical composition), resulting in increased fracture incidence. "X-linked osteoporosis due to PLS3 genetic variants is a rare disease, clinically affecting men more than women." (PMID 41563598, 2026). "In conclusion, in this study of 28 patients from 11 different families with X-linked osteoporosis due to PLS3 genetic variants, we confirmed that men are more severely affected than women." (PMID 40353206, 2025). "Sequence variants in PLS3 have so far been described in 47 families as the underlying cause for early onset osteoporosis and bone fragility." (PMID 40353206, 2025). "Despite the discovery of PLS3 as a causative gene for osteoporosis over 10 years ago and the emerging of several patient families ever since, there is still a huge gap in our understanding regarding the mechanism of PLS3-induced osteoporosis." (PMID 39273077, 2024). "In fact, it was assumed previously that cortical thinning and osteoporosis development in human and mice with PLS3 mutations or Pls3 loss resulted from PLS3-dependent disturbances of the osteoblast-regulated bone mass acquisition and mineralization." (PMID 38549711, 2024). "In the present study, we aimed to unravel if, indeed, the osteoclasts are the main cell type affected in osteoporosis caused by the loss of PLS3." (PMID 38549711, 2024). "The mRNA expression and protein abundance level of PLS3 was investigated in dermal fibroblasts of six osteoporosis patients with pathogenic PLS3 variants and five healthy individuals." (PMID 39273077, 2024). "To reveal if the osteoclasts are the major and solely cell system affected by the loss of Pls3 and are responsible for the development of osteoporosis, we generated an osteoclast-specific Pls3 KO mouse line." (PMID 38549711, 2024). "Due to the complex function of PLS3, the pathogenic mechanism leading to osteoporosis and fractures has remained largely elusive." (PMID 39273077, 2024). "This is a whole field in itself, and the question is, ‘‘what is the nosologic description of these syndromes of osteoporosis in young adult women with heterozygous variants in PLS3 or MBTPS2 or SMS’’ in their reproductive years?’’." (PMID 38942908, 2024). "In this report, we describe five new families with novel PLS3 variants leading to early-onset primary osteoporosis." (PMID 38043102, 2024). "In 2013, we demonstrated that variants in PLS3 (plastin 3, also known as T-plastin or fimbrin) are an X-linked genetic cause of nonsyndromic osteoporosis." (PMID 39273077, 2024). "Genetic testing showed an X-linked inherited osteoporosis caused by a hemizygous mutation in the PLS3 gene [c.994_995delGA (p.Asp332*)]." (PMID 38043102, 2024). "Recent studies identify PLS3 as a novel bone regulator and PLS3 mutations can lead to a rare monogenic early-onset osteoporosis." (PMID 37083757, 2023). "Males with PLS3 pathogenic variants experience severe osteoporosis and fracture at a young age (MIM#300,910), while in females with heterozygous pathogenic variants clinical presentation can vary in severity." (PMID 37277619, 2023). "PLS3 variants have been found to cause osteoporosis and OI, while abnormally high levels of PLS3 have been associated with OA." (PMID 37484945, 2023). "Although PLS3 variants were initially described as a cause of monogenic nonsyndromic osteoporosis, recent reports have suggested that they can also cause OI." (PMID 37484945, 2023). "It has been established that PLS3 variants cause syndromic and nonsyndromic osteoporosis as well as osteoarthritis." (PMID 37484945, 2023). "Plastin-3 (PLS3) is a calcium-sensitive actin-bundling protein that has recently been linked to the development of childhood-onset osteoporosis." (PMID 38089885, 2023).
osteoporosis (continued). "Studies on PLS3 mutation-induced osteoporosis and related animal models emphasize the importance of PLS3 in normal skeletal development and the maintenance of healthy bone homeostasis." (PMID 37484945, 2023). "This warrants a better understanding of the mechanism underlying osteoporosis linked to PLS3 mutations and calls for novel in vitro model systems such as we have established in this study." (PMID 38089885, 2023). "More specifically, alteration of PLS3 expression or function due to PLS3 variants have been shown to cause osteoporosis and OI." (PMID 37484945, 2023). "Abnormalities in PLS3 have been suggested to be associated with nonsyndromic osteoporosis, osteogenesis imperfecta(OI) and osteoarthritis (OA)." (PMID 37484945, 2023). "This indicates that PLS3 variants should be considered especially in males but even in females with early-onset osteoporosis." (PMID 34236445, 2022). "It is widely accepted that deficiency of PLS3 caused by pathogenic mutations will lead to early-onset osteoporosis." (PMID 35752817, 2022). "WNT1 and PLS3 pathogenic variants cause early-onset, severe osteoporosis with low BMD and frequent fractures." (PMID 36157448, 2022). "The crucial role of PLS3 in the regulation of bone mineral density has drawn attention of researchers during recent years, since pathogenic mutation or knockout of PLS3 caused early-onset osteoporosis while overexpression of PLS3 triggered osteoarthritis." (PMID 35752817, 2022). "Based on these, it is evident, that PLS3 mutations cause in affected males severe, early-onset and progressive osteoporosis predominated by multiple spinal compression fractures." (PMID 34236445, 2022). "To data, a total of 26 unique PLS3 mutations have been reported to be responsible for early-onset osteoporosis in males." (PMID 35752817, 2022). "Further studies were warranted to investigate the underlying mechanism of PLS3-related early-onset osteoporosis resulting from pathogenic mutations." (PMID 35752817, 2022). "WNT1 and PLS3 are two crucial factors regulating bone metabolism and abnormalities in their signaling have been linked to severe early-onset osteoporosis." (PMID 36157448, 2022). "In 2013, pathogenic variants in PLS3 have been reported to be associated with osteoporosis including fractures in men and mild osteoporosis in women." (PMID 34023917, 2021). "Separately, a rare single nucleotide polymorphism of the PLS3 gene was reported in association with osteoporosis in postmenopausal women." (PMID 34946798, 2021). "Recently, it was also identified in patients with a mutation in PLS3 (manuscript submitted for publication), who develop severe early onset osteoporosis." (PMID 33427926, 2021). "In heterozygous women, a rare PLS3 variant was found that resulted in a less pronounced phenotype with milder osteoporosis or normal bone density." (PMID 33802838, 2021). "PLS3 variants were found to influence bone resorption in patients with X-linked early onset low-turnover osteoporosis." (PMID 34539568, 2021). "X-linked dominant mutations in PLS3 have also been identified in families with osteoporosis and low-energy fractures, particularly in the vertebral bodies of the spine (MIM 300910)." (PMID 33945105, 2021). "In summary, most of the osteoporosis-related PLS3 variants are frameshift or nonsense mutations resulting in premature termination codons, which are followed by mRNA decay." (PMID 34023917, 2021). "PLS3 has been related to bone diseases because mutations in the encoding X-chromosomal gene PLS3 lead to osteoporosis with a mild to severe phenotype." (PMID 33802838, 2021). "It seems that the expression of PLS3 is tightly regulated since knockout or mutations cause osteoporosis, while overexpression seems to trigger osteoarthritis and various types of cancer." (PMID 34023917, 2021). "Studies indicate that pathogenic variants in the PLS3 gene, which encodes plastin 3, play a major role in bone metabolism and lead to severe early osteoporosis." (PMID 34946798, 2021).
osteoporosis (continued). "In the last years, various different PLS3 mutations have been identified to cause osteoporosis with a high variability in disease severity." (PMID 33802838, 2021). "For instance, mutations of the gene encoding plastin-3 (PLS3) were associated with severe primary osteoporosis and shown to affect bone mineral homeostasis through regulation of osteoclast activity." (PMID 32316683, 2020). "Missense mutation c.652T>G (p.C218G) in WNT1, and an X-linked form resulting from a splice mutation c.73-24T>A in PLS3 are associated with osteoporosis in children." (PMID 32733380, 2020). "To date, we have identified four unrelated Finnish families with PLS3 osteoporosis due to different PLS3 mutations." (PMID 32655496, 2020). "Of the over 20 identified osteoporosis-linked PLS3 mutations, we investigated all five that are expected to produce full-length protein." (PMID 32509377, 2020). "Assessing treatment response according to the genetic aetiology has been investigated in patients with early‐onset low‐turnover osteoporosis due to WNT1 or PLS3 mutations who were shown to respond to teriparatide therapy." (PMID 30357886, 2019). "Mutations in PLS3 cause X-linked primary osteoporosis in men and furthermore, the occurrence of osteoporosis in elderly women after the menopause is associated with a rare single nucleotide polymorphism in PLS3." (PMID 31717802, 2019). "Another gene that is linked to early-onset osteoporosis is PLS3." (PMID 41563598, 2026). "If one of the mechanisms underlying osteoporosis due to PLS3 genetic variants is indeed a decreased mechanosensing, it is conceivable that part of the defect might be overcome by strenuous physical activity." (PMID 40353206, 2025). "Likewise, mineralization defects and reduced osteoblast numbers were reported in human and rats with PLS3 mutations, leading to osteoporosis." (PMID 38549711, 2024). "Based on the high expression of the PLS3 homolog fimbrin in chicken osteocyte dendrites and their significance in mechanosensing, it is tempting to hypothesize that PLS3 variants may compromise osteocyte mechanosensitivity and lead to osteoporosis." (PMID 39273077, 2024). "Considering the increase of BMD after 15 months of teriparatide treatment in the index patient of family 2, we may conclude that PLS3 mutation-related osteoporosis can respond to teriparatide treatment." (PMID 38043102, 2024). "However, other studies have reported symptomatic osteoporosis and significant spinal compression fractures also in women with heterozygous PLS3 variants." (PMID 38043102, 2024). "In 2013, mutations in PLS3 were identified as a cause for osteoporosis." (PMID 37668887, 2024). "Thus, we can conclude that the specific depletion of PLS3 in osteoclasts is sufficient to cause a hyperresorptive activity in vitro as is observed in osteoporosis in vivo." (PMID 38549711, 2024). "However, it remains elusive, how PLS3 mutations cause osteoporosis and which cellular pathways and cell systems are mainly involved." (PMID 38549711, 2024). "Due to the gene’s X-chromosomal location, PLS3 mutations affect males more and earlier than females, but mutation-positive females may also develop symptomatic osteoporosis already in childhood or later in adulthood." (PMID 37668887, 2024). "It is important to remember that because of occasional instances of skewed X-inactivation and other genetic mechanisms, even female subjects with heterozygous X-Linked genomic variants e.g. PLS3 variants may have childhood onset osteoporosis." (PMID 38942908, 2024). "Alendronate and teriparatide treatment could be a potential treatment for early-onset osteoporosis induced by PLS3 mutation." (PMID 37083757, 2023). "Another study identified the binding of PLS3 to PLS2 which facilitates the Ca2+ release upon cell demand; a variant in the first EF-hand domain of PLS3 disrupts this interaction which weakens the regulation of intracellular Ca2+ in hFOB 1.19 cells, potentially contributing to osteoporosis." (PMID 37484945, 2023).
osteoporosis (continued). "It has been suggested that patients with WNT1 and PLS3 variants may share similar mechanisms in osteoporosis development." (PMID 37484945, 2023). "In addition to monogenic osteoporosis, PLS3 is also implicated in multifactorial age-related osteoporosis." (PMID 37484945, 2023). "In 2013 we discovered variants in PLS3 in five families as a cause of osteoporosis and fractures." (PMID 37484945, 2023). "PLS3 deficiency has been reported to cause osteoporosis and neurodegeneration." (PMID 35773742, 2022). "Instead, deletions or loss-of-function mutations in PLS3 cause osteoporosis in humans and mice." (PMID 34023917, 2021). "Moreover, PLS3 showed a significant association with osteoporosis in women upon menopause, suggesting that mutations in PLS3 not only associate with the monogenic but also the complex genetic trait of osteoporosis." (PMID 34023917, 2021). "Up to date, 27 mutations in PLS3 are associated with early-onset osteoporosis." (PMID 34023917, 2021). "Therefore, loss of Pls3 from these additional bone cells could also contribute to the cause of osteoporosis." (PMID 38549711, 2024). "However, it remains largely unknown how PLS3 mutations cause osteoporosis and which function PLS3 plays in bone homeostasis." (PMID 38549711, 2024). "Thus, the loss of PLS3 in alternative bone cell types might contributes to the osteoporosis phenotype in ubiquitous Pls3 KO mice." (PMID 38549711, 2024). "Thus, our results indicate that PLS3 plays an important role in the regulation of bone microstructure and bone strength, and we provide a novel animal model for the study of X-linked early-onset osteoporosis." (PMID 37083757, 2023). "Altogether, our data suggest that PLS3 contributes to osteoblast mineralization by regulating the mechanosensitive response of osteoblasts to increasing stiffness of their ECM, which could explain the correlation between PLS3 mutation and early onset osteoporosis." (PMID 38089885, 2023). "Despite mounting evidence that the deficiency of normal PLS3 in patients with pathogenic mutations leads to early-onset osteoporosis, whether abnormal PLS3 level was associated with osteoporosis in individuals without pathogenic mutations remains to be elucidated." (PMID 35752817, 2022). "We previously demonstrated that the ubiquitous Pls3 KO in mice results in osteoporosis and strongly impairs the osteoclast function." (PMID 38549711, 2024). "Recently, it was shown that whole body deletion of Pls3 in mice (ubiquitous Pls3 knockout mice) leads to osteoporosis, characterized by increased bone thickness and stiffness in these mice." (PMID 38549711, 2024). "This study aims to comprehensively characterize the osteoclasts and the bone phenotype of the generated mouse model and compare these findings to the ubiquitous Pls3 KO mice to gain a deeper understanding of the role of PLS3 in the osteoporosis pathomechanism." (PMID 38549711, 2024). "Mainly osteoclasts were impacted in their function However, it has not been proven if osteoclasts are the major cell type affected and responsible for osteoporosis development in ubiquitous Pls3 KO mice." (PMID 38549711, 2024). "Due to its X-chromosomal inheritance, PLS3-induced osteoporosis has more severe effects on males than females, although heterozygous carrier females also suffer from EOOP." (PMID 37083757, 2023). "In this study, we aim to gain insight into how PLS3 contributes to the development of childhood osteoporosis by investigating the role of calcium-sensitive actin bundling of PLS3 in osteoblast mineralization." (PMID 38089885, 2023). "Pathogenic variants in the LRP5, PLS3, or WNT1 genes can significantly affect bone mineral density, causing monogenic osteoporosis." (PMID 37277619, 2023). "Identification of CNVs in genes previously associated with osteoporosis (e.g. RUNX2, COL1A2, and PLS3) has confirmed their importance in bone remodelling." (PMID 36795294, 2023).